NRAS (NRAS proto-oncogene, GTPase)
Diseases named in the same sentence as NRAS in open-access papers (continued):
Sharing a sentence is not in itself a finding about the gene and the disease.
melanoma (continued). "However, as S73/S409 are target sites for ERK‐/RSK1‐mediated phosphorylation, assessing the BAC transgenic mice in the context of deregulated MAPK signalling in an NRAS and/or BRAF mutant background will be of major importance and could reveal essential regulatory mechanisms relevant for melanoma." (PMID 25818589, 2015). "Our largest comprehensive molecular analysis of clinical stage III melanoma revealed that BRAF and NRAS mutational status is not a prognostic marker in stage III melanoma patients with macroscopic nodal involvement, but may have implications for potential adjuvant therapy." (PMID 24959217, 2014). "Furthermore, we were interested in determining if dinaciclib could have therapeutic efficacy in an NRAS mutant melanoma, as there are currently no effective therapies for these types of tumors." (PMID 23527225, 2013). "Our studies with melanoma tumor cells that are BRAFV600E/K and BRAFWT showed that, paradoxically, while PLX4032 inhibited ERK1/2 in the highly sensitive BRAFV600E/K, it activated the pathway in the resistant BRAFWT cells, via RAF1 activation, regardless of the status of mutations in NRAS or PTEN." (PMID 20149136, 2010). "Although NRAS-mutant melanomas represent the most aggressive and second most common melanoma subtype behind BRAF mutant melanomas, there remain no available NRAS-targeted therapies." (PMID 39379700, 2024). "Immunostains were strongly positive for SOX10 and PRAME (preferentially expressed antigen of melanoma); while negative for BRAF, VE1, NRAS, Q61L, and DOG1." (PMID 38933829, 2024). "In the literature, the triple-wild-type melanoma (TWM) refers to those where BRAF, NRAS and NF1 are not mutant." (PMID 36980598, 2023). "While at different levels, all the PDX cells show S2R expression, regardless of their genetic background (MM13/MM16 are NRAS-mutant and MM2/MM27 BRAF-mutant melanomas)." (PMID 37298633, 2023). "Our results demonstrate that NRAS expression is significantly correlated with MALAT1 expression in both non-cancerous skin (p < 0.001) and melanoma (p < 0.001)." (PMID 37235843, 2023). "For instance, p38 plays a tumor suppressive role in NRAS-mutant melanoma but not in BRAF-mutant melanoma, even though BRAF and NRAS are part of the same MAPK pathway." (PMID 36765834, 2023). "In our dataset, melanomas with FER amplification had frequent NF1 inactivation but lacked BRAF and NRAS alterations." (PMID 35706047, 2022). "Furthermore, we confirmed elevated expression of human DGAT1 but not DGAT2 mRNA in melanoma tumors relative to both skin and nevi and elevated DGAT1 protein in human melanoma cell lines relative to primary melanocytes irrespective of NRAS or BRAF mutational status." (PMID 35732120, 2022). "Moreover, this location of the melanoma is an entirely distinct entity from skin melanoma and melanomas of the nasal cavity, while cervix melanomas also have some particularities, and do not suffer recurrent KIT mutations, or mutations of the NRAS and SF3B1 genes." (PMID 34209084, 2021). "We saw that XAF1 knockdown increased proliferation of NRAS, but not BRAF mutant melanoma cells, yet we acknowledge that this effect was observed in a limited number of cell lines." (PMID 33734579, 2021). "The NRAS inhibitor salirasib, which modifies RAS-GTP binding to cell membranes by competition, has not been assessed in a clinical trial for melanoma." (PMID 33804655, 2021). "GAB2 CNV gains have also been reported in non-sun-damaged melanoma, including AMs and MUs, and have been reported to be mutually exclusive of BRAF, NRAS, and KIT aberrations." (PMID 33826614, 2021). "In line with prognosis, genetic alterations occurring in mucosal melanoma are different than those of cutaneous wild-type melanoma (BRAF, NRAS and NF1 negative)." (PMID 34571863, 2021).
melanoma (continued). "Of the activating RAF1-fusion melanomas, 98% (n = 39) were wild type for BRAF, NRAS, and NF1 genomic alterations (triple wild type) vs. 26% (n = 1843/7079) of the melanoma cohort without RAF1 fusion (p < 0.0001, Fisher’s exact test)." (PMID 32123303, 2020). "Importantly, this striking effect on SOX10 protein levels was present in all melanoma cultures, irrespective of whether they harbor activating BRAF p.V600E, NRAS p.Q61K, or both mutations, and irrespective of whether they are sensitive to MAPK inhibition or resistant." (PMID 32238882, 2020). "Only in two samples the panel was covered less than 90% but without involving the main targets for melanoma as BRAF and NRAS genes." (PMID 31547467, 2019). "To do this, we analyzed BRAF, NRAS and TERT promoter mutant ctDNA using serial blood samples from melanoma patients with and without confirmed disease recurrence." (PMID 30719207, 2019). "Similar results were obtained in other BRAFV600E-positive melanoma cells such as G361 and SK-MEL-5, but not in MeWo and NRAS mutant SK-MEL-2 cells that contain WT BRAF." (PMID 30979895, 2019). "We next explored the biological effects of blocking TCF19 in NRAS‐mutant cells, as the role of this PHD‐type zinc finger‐containing domain transcription factor has not been previously investigated in melanoma." (PMID 29650805, 2018). "Additionally, when we plotted the top 65 DEGs, we noticed that sample clustering was independent of mutations in the RAS (KRAS, NRAS, and HRAS) and NF1 genes, which have been described to modify gene expression patterns in melanoma, avoiding expression bias that might be caused by those genes." (PMID 30242167, 2018). "Seventeen melanoma lines lacked both PD-L1 and PD-L2 basal expression, including 5/10 (50%) BRAF/NRASWT, 4/11 (36%) BRAFV600-mutant, 1/10 (10%) NRAS-mutant, and 7/8 (87.5%) uveal cell lines." (PMID 29977240, 2018). "In summary, we demonstrated that both small molecule SR4 and niclosamide have anti-proliferative and pro-apoptotic activities against melanoma irrespective of BRAF and NRAS status." (PMID 30651927, 2018). "Amplification of NRAS was detected in 6.3% (2/32) and 9.5% (2/21) of BRAF/NRAS WT and High non-HET melanomas, respectively." (PMID 28668077, 2017). "The interval between the diagnosis of the initial melanoma to regional nodal metastasis was not significantly different between the BRAF-mutant and -WT patients (median, 10 months; P=0.29) or between NRAS-mutant and -WT patients (median, 10 months; P=0.34)." (PMID 24959217, 2014). "While BRAF inhibitors are initially effective for BRAF-mutant melanoma, no FDA-approved targeted therapies exist for BRAF-inhibitor-resistant BRAFV600, NRAS mutant, or wild-type melanoma." (PMID 25142146, 2014). "Based on the observation that the CDK4/6 pathway is frequently altered in melanoma, CDK4/6 inhibitors have emerged as potential agents for treating patients with NRAS-mutant and BRAF-wild-type tumors that have not lost the tumor suppressor retinoblastoma protein (pRb)." (PMID 40904502, 2025). "In melanomas that arise outside of an epithelium, such as in the dermis and eye, MAPK pathway activation is most frequently achieved through the activation of Gαq/11 signaling, rather than directly through BRAF or NRAS." (PMID 39804140, 2025). "Immunoblot analysis showed that NRAS ASO-1 did not substantially affect p-AKT levels, highlighting the specific inhibitory effect of ASO-mediated NRAS-mRNA depletion on the MAPK-signaling axis in NRAS-mutant melanoma." (PMID 40473796, 2025). "However, even dual inhibition of RAF/EGFR in CRC can be overcome by wild-type NRAS amplification, which has been identified as a unique adaptive mechanism in CRC, but not in melanoma." (PMID 37920169, 2023).
melanoma (continued). "In addition, class 3 BRAF mutations were more prevalent in HRAS-mutant salivary gland (5%), and bladder (9%), and melanoma (11%) cancers, whereas none were present in the respective KRAS- and NRAS-mutant tumors (p<0.05 for all)." (PMID 37503077, 2023). "In addition, therapeutic options for some non-eligible melanoma patients (for example, RAS mutant or triple BRAF/NRAS/NF1 wild-type melanoma patients) are more limited." (PMID 35159327, 2022). "Finally, PD-L1 expression is constitutively elevated in KRAS G13D but not in NRAS Q61K or MEK1 Q56P A375 cells, pointing to a possible role for immune checkpoint inhibition in melanomas carrying this specific biomarker." (PMID 36358868, 2022). "In fact, melanoma cell lines treated for only 24 h or from 48 to 72 h with BRAFi, MEKi, or ERKi, display spindle-shaped and/or flat morphology, regardless of the MAPK oncogenic driver (BRAF or NRAS mutant)." (PMID 35159327, 2022). "These diverse mechanisms of action of cannabinoids may serve as a potential therapy in case of triple negative melanomas (harboring wild-type BRAF, NRAS and PTEN), which do not respond to a novel immunotherapy." (PMID 34264513, 2021). "This either means that the same rules do not apply in melanoma, that oncogenic KRAS and NRAS differ or that the mechanism of action of karonudib extends outside MTH1 inhibition, e.g., the proposed microtubule disruption caused by inhibitors of the same class as karonudib." (PMID 30042422, 2018). "Disomy of NRAS/chromosome 1 (with or without polysomy in few cells) were detected in 59.4% (19/32) of BRAF/NRAS WT, 50% (15/30) of HET, but in only 28.6% (6/21) of High non-HET melanomas (P = 0.08)." (PMID 28668077, 2017). "In contrast with what is observed in established control melanoma cells, NRAS/CRAF complexes were strikingly much less abundant than NRAS/BRAF complexes in melanocytes at P10, thus explaining why CRAF can compensate for BRAF absence in melanoma cells but not in early melanocytic lesions." (PMID 28497782, 2017). "In total, only 9.6% of all cases in the cohort were negative for either of the genetic changes in BRAF, NRAS, NF1 and KIT, indicating that the majority of melanomas could potentially have activated MAPK pathway through these genetic alterations." (PMID 25909218, 2015). "To test whether the same association could be observed in clinical samples, we investigated MHC-II/HLA-DR expression by IHC in a tissue microarray (TMA) of melanoma patient samples (n=67) with known BRAF and NRAS genotypes who largely had not received immune therapy." (PMID 26822383, 2016). "The lack of antitumor effect of ZA in vivo on the NRAS mutant and BRAF mutant and PTEN null melanoma cells may be explained by the fact, that around 50–60% of ZA accumulates in the skeleton and the remaining part is excreted in the first 24hs after drug administration." (PMID 25646931, 2015).
colorectal cancer (252 papers, 2009 to 2026). A primary or metastatic malignant neoplasm that affects the colon or rectum. "In summary, the functional consequences of KRAS and NRAS mutations in colorectal cancer are multifaceted, influencing not only intracellular signal transduction and therapeutic response but also tumor progression and systemic disease behavior." (PMID 40731832, 2025). "In this study, we explored the prognostic impacts of HIF-1α, LOX and ITGA5 expression in the tumor microenvironment and their relationship with KRAS/NRAS/BRAF mutation status in colorectal cancers." (PMID 39857068, 2025). "For unexplained reasons, KRAS mutations are predominantly found in pancreatic cancer, colorectal cancer, and adenocarcinoma of the lung, whereas mutated NRAS is predominantly found in a subset of acute leukemias and in myelodysplastic syndromes." (PMID 40694264, 2025). "Although less frequent than KRAS mutations, neuroblastoma ras viral oncogene homolog (NRAS) mutations occur in 5–9% of colorectal cancer cases, typically associated with tumor progression and resistance to anti-EGFR therapies in KRAS wild-type tumors." (PMID 39684219, 2024). "To verify the inhibitory effect of JPHTF on the growth of CRC tumors carrying RAS mutations, we injected a human colorectal cancer cell carrying NRAS mutations into two groups of mice." (PMID 38974035, 2024). "KRAS and NRAS mutations are known to be the most frequent actionable mutations observed in colorectal cancer." (PMID 35474548, 2022). "Some of the commonly identified mutations associated with targeted therapies include, e.g., mutations in BRAF in cutaneous melanoma; KRAS, BRAF, and NRAS in colorectal cancer; and EGFR mutations and ALK and ROS1 gene rearrangements in lung adenocarcinomas." (PMID 35627184, 2022). "For example, mutations of KRAS and NRAS predict resistance to anti-EGFR antibodies in colorectal cancers, and patients with lung adenocarcinoma that harbor EGFR mutations or ALK rearrangements have shown remarkable efficacy in relevant targeted drug therapy." (PMID 36741696, 2022). "UnlikeKRASmutations that are strongly implicated in colorectal cancer,NRAS alterations are rare and, to date, limited data on their mutation prevalence are available." (PMID 32892548, 2021). "In this context,NRAS, a member of theRASfamily, is found to be mutated in 1%–7% of colorectal cancers." (PMID 32892548, 2021). "Numerous studies have reported that KRAS and NRAS mutations occur respectively in 45% and 5–8% of worldwide colorectal cancer patients." (PMID 33784337, 2021). "CT image texture parameters of colorectal cancer have certain correlation with KRAS/NRAS/BRAF gene mutations in colorectal cancer, and the texture parameters extracted from MRI images can help predict TCGA/TCIA molecular subtypes in breast cancer." (PMID 34307164, 2021). "In our cohort, only 4 patients had colorectal cancer with KRAS/NRAS mutations, three of them (all B2M-wt) received ICB therapy and showed PR as best response." (PMID 34168989, 2021). "The NRAS E132K mutation was identified in three tumor samples from a prospective study of Filipino young-onset, sporadic colorectal cancer patients 45 years old and under (D. L. Sacdalan and R.L. Garcia, unpublished results)." (PMID 32620824, 2020). "This study reports the functional characterization of the non-canonical KRAS G12S and KRAS A59T mutations, and the novel KRAS Y137C and NRAS A11V mutations identified in Filipino colorectal cancer patient tumor samples." (PMID 31816869, 2019). "Three previous studies reported their results using the NRAS-BRAF-EGFR or NRAS-BRAF Mutation Assay in colorectal cancer and one in metastatic melanoma." (PMID 31415669, 2019). "This feature has been investigated in an adenomatous polyposis coli (APC)-deficient mouse model where mutations of KRAS were able to promote the development of colorectal cancers, while NRAS mutations were ineffective." (PMID 31803624, 2019).
colorectal cancer (continued). "In colorectal cancer, NRAS mutations are found less often, in up to 4% of the cases, and also correlate with less favorable clinical outcome, enforcing the use of special treatment strategies." (PMID 29682098, 2018). "NRAS mutations contribute to the response to cetuximab treatment in colorectal cancer cells by reducing patients survival." (PMID 27556696, 2016). "The four genes linked to colorectal cancer (NRAS, PIK3CA, MCC, APC) all show lower methylation in the AA/YRI groups." (PMID 25742137, 2015). "Vemurafenib, a BRAF inhibitor, reduced pS-EphA2 in cells harbouring BRAF mutation, but rather increased pS-EphA2 in NRAS-mutated SK-MEL-2 cells as well as in KRAS-mutated DLD-1 human colorectal cancer cells." (PMID 26158630, 2015). "Unlike KRAS mutations, which constitute a large percentage of the mutations in colorectal cancer, NRAS mutations are rare." (PMID 26691448, 2015). "According to current clinical guidelines mutational analysis for KRAS and NRAS is recommended prior to EGFR-directed therapy of colorectal cancer (CRC) in the metastatic setting." (PMID 26220423, 2015). "Previous studies reported that BRAF, KRAS, and NRAS mutations occur in 10%–15%, 35–40%, and 2–7% of colorectal cancers, respectively." (PMID 26090613, 2015). "The BRAF, KRAS, and NRAS mutations are widely recognized to be the major causes of RAS/RAF/MEK/ERK pathway dysregulation in colorectal cancer." (PMID 26090613, 2015). "Can CT-based radiomics signature predict KRAS/NRAS/BRAF mutations in colorectal cancer?" (PMID 38608072, 2024). "Prediction of KRAS/NRAS/BRAF mutations in colorectal cancer (CRC)." (PMID 35740526, 2022). "KRAS mutation is more common than NRAS mutation in colorectal carcinoma." (PMID 35328664, 2022). "We examined and analyzed mutation status of KRAS/NRAS/ BRAF in colorectal cancer tissues." (PMID 33816307, 2021). "KRAS and NRAS mutated colorectal cancers (CRC) are known to be resistant to epithelial growth factor receptor (EGFR)-targeted therapy, suggesting that this type of treatment may also be ineffective in PMP." (PMID 28426742, 2017). "Moreover, as additional RAS-activating mutations, NRAS mutations have been reported to predict the response in patients with colorectal cancer treated with anti-EGFR therapeutics." (PMID 28147317, 2017). "Mutations in other genes, such as PIK3CA and NRAS may also influence anti-EGFR treatment efficacy in colorectal cancer." (PMID 25568935, 2015). "For example, standard treatment guidelines recommend KRAS and NRAS testing for colorectal cancer patients and that patients with KRAS- and NRAS-mutated colorectal cancer not be treated with epidermal growth factor receptor inhibitors such as cetuximab and panitumumab." (PMID 25593991, 2014). "In a previous study for quality assessment, we confirmed that KRAS and NRAS mutations may be present in the same population or different subpopulations of colorectal cancers according to an operating procedure proposed for validation of unexpected coexisting mutations." (PMID 32333643, 2020). "Among the common mutations in colorectal cancers, NRAS mutations were frequent (p.Glu61Lys, p.Glu61Arg, and p.Glu61Leu missense/common mutations in C1, C3, and C7, respectively), although this event has been previously reported to be relatively rare (<5%) in colorectal cancers." (PMID 32023847, 2020).